APBA3 (amyloid beta precursor protein binding family A member 3)
Description:
May modulate processing of the amyloid-beta precursor protein (APP) and hence formation of APP-beta. May enhance the activity of HIF1A in macrophages by inhibiting the activity of HIF1AN.
Synonyms: MINT3; X11L2; MGC:15815
Tractability: Small molecule: a structure with a bound ligand is known. Antibody: its Gene Ontology location is reachable by antibodies, with medium confidence.
Gene: Protein-coding gene on chromosome 19 (3,750,772 to 3,761,700, reverse strand). Ensembl gene ENSG00000011132.
Subcellular location: Cytoplasm, perinuclear region
Subcellular location (Human Protein Atlas): Vesicles
Pathways (Reactome):
Neuronal System: Neurexins and neuroligins
Gene Ontology:
Molecular function: enzyme binding; enzyme inhibitor activity; protein binding; amyloid-beta binding
Biological process: negative regulation of catalytic activity; chemical synaptic transmission
Cellular component: perinuclear region of cytoplasm; cytoplasm; dendritic spine; plasma membrane
Genetic constraint (gnomAD): Loss-of-function variants: 45 observed, 46.64 expected, observed/expected ratio (o/e) 0.96, 90% interval 0.76 to 1.24. The upper end of that interval is the gene's LOEUF score, 1.24, which puts it in group 5 of 6, group 1 being the genes least tolerant of losing a copy. Missense variants: 865 observed, 743.11 expected, observed/expected ratio (o/e) 1.16, 90% interval 1.1 to 1.23. Synonymous variants: 370 observed, 312.2 expected, observed/expected ratio (o/e) 1.19, 90% interval 1.09 to 1.29.
Homologues: Orthologues: chimpanzee APBA3 (98% identical), macaque APBA3 (96% identical), dog APBA3 (87% identical), pig APBA3 (85% identical), mouse Apba3 (76% identical), rat Apba3 (72% identical), tropical clawed frog apba3 (53% identical), zebrafish APBA3 (49% identical), Drosophila melanogaster X11Lbeta (44% identical), Caenorhabditis elegans lin-10 (39% identical). Paralogues in human: APBA1 (48% identical), APBA2 (46% identical), SDCBP (13% identical), SDCBP2 (12% identical).
Diseases named in the same sentence as APBA3 in open-access papers:
APBA3 is named in the same sentence as 31 diseases in open-access papers, as found by Europe PMC text mining. Sharing a sentence is not in itself a finding about the gene and the disease. The quoted sentences say what the papers report.
influenza pneumonia (4 papers, 2016 to 2021). "Mint3/Apba3 depletion activates AMPK through IκBα, and Mint3-deficient mice exhibit an improvement influenza pneumonia with a reduced inflammatory response." (PMID 34066434, 2021). "Mint3/Apba3 depletion activates AMPK through IκBα and Mint3-deficient mice exhibits improved influenza pneumonia with reduced inflammatory." (PMID 34066434, 2021). "AMPK plays a role in the excessive inflammatory cytokine/chemokine levels in Mint3/Apba3 depletion models of severe pneumonia due to influenza virus." (PMID 30404221, 2018).
melanoma (2 papers, 2019 to 2021). A malignant, usually aggressive tumor composed of atypical, neoplastic melanocytes. "In syngeneic melanoma models, glycolytic macrophages upregulate the expression of E-selectin on the endothelium through HIF-1 and its activator APBA3, such that APBA3 depletion in monocytes reverses this effect in association with reduced metastasis to lung." (PMID 31497019, 2019).
Alzheimer disease (1 paper, 2013). A progressive, neurodegenerative disease characterized by loss of function and death of nerve cells in several areas of the brain leading to loss of cognitive function such as memory and language. "It is interestingly to note that three (APBA2, APBA3 and NINJ2) of these genes are correlated with Alzheimer’s disease." (PMID 24367640, 2013).
Borderline personality disorder (1 paper, 2013). A personality disorder characterized by impulsive behavior and unpredictable, capricious mood. "Thus it is tempting to speculate that epigenetic alteration of APBA2 and APBA3 may contribute to borderline personality disorder." (PMID 24367640, 2013).
cancer (14 papers, 2013 to 2025). A tumor composed of atypical neoplastic, often pleomorphic cells that invade other tissues. "Aberrant methylation of APBA2/MINT2 and APBA3/MINT3 were not previously reported in psychiatric disease however frequently observed in cancer." (PMID 24367640, 2013). "In addition, APBA3 promotes aerobic glycolysis by activating hypoxia-inducible factor 1 (HIF-1) in macrophages; therefore, inhibition of APBA3 in macrophages contributes to suppression of cancer cell metastasis." (PMID 32316112, 2020).
APBA3 also shares sentences with these, for which no sentence is quoted: tumor (9 papers); breast carcinoma (6); pancreatic cancer (5); infection (3); bladder cancers (1); epidermoid carcinoma (1); fibrosarcoma (1); hepatocellular carcinoma (1); Hyperglycemia (1); invasive breast carcinoma (1); listeriosis (1); liver cancer (1); liver cirrhosis (1); lung carcinoma (1); lung diseases (1); lymph node metastasis (1); Ovarian Failure (1); papillary kidney carcinoma (1); prostate carcinoma (1); psychiatric disease (1); rheumatoid arthritis (1); triple-negative breast carcinoma (1); type-2 diabetes (1); urothelial bladder cancer (1); urothelial carcinoma (1); viral infection (1).